ACAT2 (acetyl-CoA acetyltransferase 2)
Description:
Involved in the biosynthetic pathway of cholesterol.
Tractability: Small molecule: a structure with a bound ligand is known. PROTAC: ubiquitination databases record sites on it; its protein half-life has been measured.
Target class: Enzyme; Transferase
Gene: Protein-coding gene on chromosome 6 (159,761,981 to 159,779,821, forward strand). Ensembl gene ENSG00000120437.
Subcellular location: Cytoplasm, cytosol
Subcellular location (Human Protein Atlas): Cytosol; Nucleoplasm
Pathways (Reactome):
Metabolism: Lanosterol biosynthesis
Gene Ontology:
Molecular function: acetyl-CoA C-acetyltransferase activity; protein binding; acyltransferase activity; acyltransferase activity, transferring groups other than amino-acyl groups
Biological process: farnesyl diphosphate biosynthetic process, mevalonate pathway; lipid metabolic process; fatty acid metabolic process
Cellular component: cytoplasm; extracellular exosome; cytosol
Genetic constraint (gnomAD): Loss-of-function variants: 24 observed, 34.1 expected, observed/expected ratio (o/e) 0.7, 90% interval 0.51 to 0.99. The upper end of that interval is the gene's LOEUF score, 0.99, which puts it in group 4 of 6, group 1 being the genes least tolerant of losing a copy. Missense variants: 416 observed, 466.19 expected, observed/expected ratio (o/e) 0.89, 90% interval 0.82 to 0.97. Synonymous variants: 146 observed, 159.25 expected, observed/expected ratio (o/e) 0.92, 90% interval 0.8 to 1.05.
Gene-disease validity (ClinGen):
ClinGen rates the evidence that ACAT2 causes each of these diseases.
acetyl-CoA acetyltransferase-2 deficiency (inheritance undetermined): No Known Disease Relationship.
Homologues: Orthologues: chimpanzee ACAT2 (99% identical), macaque ACAT2 (96% identical), dog ACAT2 (90% identical), guinea pig ACAT2 (89% identical), mouse Acat2 (88% identical), rat Acat2 (87% identical), rabbit ACAT2 (86% identical), mouse Acat3 (86% identical), pig ACAT2 (86% identical), rat Acat2l1 (84% identical), tropical clawed frog acat2 (72% identical), zebrafish acat2 (72% identical), and 1 more. Paralogues in human: ACAT1 (44% identical), ACAA2 (43% identical), ACAA1 (42% identical), HADHB (33% identical).
Diseases named in the same sentence as ACAT2 in open-access papers:
ACAT2 is named in the same sentence as 75 diseases in open-access papers, as found by Europe PMC text mining. Sharing a sentence is not in itself a finding about the gene and the disease. The quoted sentences say what the papers report.
atherosclerosis (18 papers, 2008 to 2024). A disease characterized by the build-up of fatty material and calcium deposition in the arterial wall resulting in partial or complete occlusion of the arterial lumen. "ACAT2 is expressed in hepatocytes, and ACAT2-deficient mice had low serum cholesterol and were protected from atherosclerosis and hepatic lipid accumulation." (PMID 36551908, 2022). "Studies have shown that atherosclerosis is reduced in mouse atherosclerosis models when Acat2 is deficient; Acat2-deficient mice are resistant to diet-induced hypercholesterolemia or cholesterol stone formation." (PMID 33679891, 2021). "It has been reported that inflammation is closely related to ACAT2 activity and downregulating ACAT2 is associated with lowering cholesterol and preventing atherosclerosis." (PMID 34490291, 2021). "This concept is largely fuelled by studies which have shown that ACAT2-deficient mice, when compared to wild type mice, have reduced hepatic CE and are protected against diet-induced atherosclerosis." (PMID 33007859, 2020). "It is observed in an atherosclerosis model of Apo E-deficient mice that the formation of atherosclerosis can be prevented by simultaneous knockout of ACAT2, suggesting that ACAT2-mediated cholesterol esterification is important for atherosclerosis." (PMID 22649479, 2012). "In addition, genes Soat1 and Soat2 are known to encode ACAT1 and ACAT2 enzymes in catalyzing the formation of cholesteryl esters, an important process during atherosclerosis formation." (PMID 19835623, 2009). "In vivo, PPPA-mediated ACAT2 inhibition was shown to protect the mice from atherosclerosis, ACAT2 enzyme mediates in lipid metabolism and is localized in the liver and intestines." (PMID 34394757, 2021). "Pyripyropenes, in particular pyripyropene A, were discovered as a highly potent selective inhibitor of the ACAT-2 isoform, which was considered a new therapeutic target for the treatment and prevention of hypercholesterolemia and atherosclerosis." (PMID 30366473, 2018). "ACAT2 is the major cholesterol-esterifying enzyme that plays a critical role in preventing murine atherosclerosis and hypertriglyceridemia." (PMID 30397542, 2018). "So ACAT2 plays a critical role in the production of atherogenic apoB-containing lipoproteins and that ACAT2-specific inhibitors are extremely effective in preventing murine atherosclerosis." (PMID 24505463, 2014). "ACAT2 plays an important role in efficient cholesterol absorption, lipoprotein metabolism, and atherosclerosis." (PMID 25050817, 2014). "For an isoform of ACAT, ACAT-2 has been proven to be a protective factor in atherosclerosis in animal models." (PMID 24577316, 2014). "PPPA, an acyl-CoA, was a selective inhibitor of cholesterol acyltransferase 2-selective inhibitor (ACAT2), the selective inhibition of ACAT2 in intestine and liver could effectively combat atherosclerosis." (PMID 38686108, 2024). "Lower levels of Acat2 activity in the human liver can delay the development of atherosclerosis; therefore, improving the stability of Acat2 may be an effective treatment strategy for type II diabetes." (PMID 33679891, 2021). "Previous studies have found that deletion of ACAT-2 may delay the development of atherosclerosis in animal models." (PMID 30696703, 2019). "Whereas ACAT-2 deficiency in mice may restrict synthesis of CE and reduce the accumulation of CE in the plasma lipoproteins and atherosclerosis development in ACAT-2–/–/ApoE–/– mice." (PMID 30696703, 2019).
atherosclerosis (continued). "Therefore, pharmacological inhibition of ACAT is expected to suppress foam cell formation in arterial walls by suppressing macrophage ACAT-1 and cholesterol absorption by suppressing intestinal ACAT-2, thereby inhibiting atherosclerosis." (PMID 24577316, 2014). "After 20 weeks of the diet, the control group showed signs of atherosclerosis signs, whereas ACAT2−/− mice were protected against atherosclerosis regardless of the administered fat." (PMID 34063343, 2021).
breast carcinoma (12 papers, 2019 to 2025). "Recent years, many studies have found that aberrantly expressed ACAT2 is associated with carcinogenesis and progression, such as hepatocarcinoma, clear cell renal cell carcinoma, colorectal cancer, breast cancer, and so on." (PMID 38178203, 2024). "Inhibition of HDAC induces transcriptional repression of high copy number genes in breast cancer and ACAT2 gene encode enzymes involved in lipid metabolism." (PMID 31487323, 2019). "Recent years, studies have shown that ACAT2 is aberrantly expressed in tumor, such as hepatocarcinoma, clear cell renal cell carcinoma, colorectal cancer and breast cancer." (PMID 38178203, 2024). "The acyl-coenzyme A (CoA): cholesterol acyltransferase 2 (ACAT2) promoted proliferation and metabolism in hepatocellular carcinoma, colorectal cancer, and breast cancer." (PMID 37259038, 2023). "Leptin has been shown to enhance breast cancer cells proliferation, migration, and invasion by up-regulating acetyl coenzyme A acetyltransferase 2 (ACAT2) via the PI3K/AKT/SREBP2 signaling pathway." (PMID 35743814, 2022). "It has been confirmed that ACAT2 could promote the proliferation, migration and invasion of breast cancer cells after being up-regulated by leptin, which might be a potential biomarker and precision treatment target." (PMID 34790227, 2021). "Interestingly, a recent study has been suggested that leptin activates SREBP‐2 and thereby promotes migration and invasion of breast cancer cells via upregulation of acetyl‐CoA acetyltransferase 2 (ACAT2)." (PMID 33226729, 2021). "Also, leptin potentiated the proliferation, migration, and invasion of breast cancer cells via upregulating ACAT2 through the PI3K/AKT/SREBP2 signaling pathway." (PMID 33371368, 2020). "Furthermore, other recent study has proposed leptin to enhance the proliferation, migration and invasion of breast cancer cells via acetyl-CoA acetyltransferase 2 (ACAT2) up-regulation through the PI3K/AKT/SREBP2 signaling pathway." (PMID 31380268, 2019). "Another study also revealed that leptin elevated expression of SREBP-2 via PI3K/AKT signaling, thus upregulating acetyl-CoA acetyltransferase 2 (ACAT2) to favor the migration and invasion of breast cancer cells." (PMID 34888248, 2021). "Additionally, the other research has recently suggested that leptin promotes breast cancer cell proliferation, migration, and invasion via the up-regulation of PI3K/AKT/SREBP2 signal pathway through acetyl-CoA acetyltransferase 2 (ACAT2)." (PMID 33935708, 2021). "Taken together, our data suggest that despite the appropriate inhibition of ACAT2, the known effects of avasimibe on CYP450 activity enhanced fluvastatin metabolism and negated any benefit to dual targeting of the cholesterol synthesis pathway for breast cancer prevention." (PMID 40141147, 2025). "On the other hand, leptin-induced non-secreted proteins, such as OBR, PKM2, ACAT2, and SREBP-1, are also important for breast cancer evolution." (PMID 33371368, 2020).
Hypercholesterolemia (11 papers, 2011 to 2024). An increased concentration of cholesterol in the blood. "Thus, as the Acat2 level in liver is decreased during HFD-induced obesity, our results suggest that liver-targeted adenoviral Acat2 overexpression represents a potential therapeutic strategy for obesity and its associated hypercholesterolaemia." (PMID 36378328, 2023). "A study has reported ACAT2 is a target for treatment of coronary heart disease related to hypercholesterolemia." (PMID 38178203, 2024). "Acat2 overexpression provides a potential therapeutic strategy for obesity and hypercholesterolaemia, yet the current methods and results are limited." (PMID 36378328, 2023). "ACAT-2 is the most preferred target for studies related to hypercholesterolemia and coronary heart diseases." (PMID 31885643, 2019). "ACAT2-knockout mice, compared to wild-type mice, absorbed less cholesterol and they were resistant to diet-induced hypercholesterolemia." (PMID 19228775, 2011). "Further studies conducted on different mouse models should be performed, including high-cholesterol diet, ob/ob, db/db and LDL-cholesterol-receptor knockout mice (hypercholesterolaemia), to investigate the effects of hepatic Acat2 overexpression in metabolic disorders." (PMID 36378328, 2023). "Thus, adenoviral Acat2 overexpression in the liver may be a potential therapeutic tool in the treatment of obesity and hypercholesterolaemia." (PMID 36378328, 2023). "Taken together, hepatic Acat2 overexpression elevates the metabolic rate and protects mice from HFD-induced glucose intolerance and hypercholesterolaemia." (PMID 36378328, 2023). "Spirulina is known to reduce the effects of hypercholesterolemia by regulating SREBP-2, ACAT-2, and HMG-CoA." (PMID 31885643, 2019). "In addition, Acat2-overexpressing mice gained less body weight, had a higher metabolic rate after HFD feeding and were protected from HFD-induced glucose intolerance and hypercholesterolaemia." (PMID 36378328, 2023).
Obesity (7 papers, 2016 to 2025). Accumulation of substantial excess body fat. "This system efficiently delivered ACAT2 siRNA specifically to the mouse small intestine and effectively suppressed intestinal lipid absorption, addressing obesity." (PMID 41345744, 2025). "As ACATs play a key role in the cholesterol metabolic pathway, we next surveyed the expression level of ACAT2 in liver after diet-induced obesity (DIO)." (PMID 36378328, 2023). "The results demonstrated that ACAT2-mediated cholesterol metabolism might be inhibited and contribute to the lipid disorder during obesity." (PMID 36378328, 2023). "Acat2 and Scp2 are involved in lipid metabolism while Acot11 is involved in obesity." (PMID 27699085, 2016). "Therefore, ACAT2 inhibitors may be tested in pork quality improvement, body fat distribution research and obesity research." (PMID 35204738, 2022).
clear cell renal cell carcinoma (4 papers, 2022 to 2024). "Downregulation of ACAT2 is associated with poor prognosis in clear cell renal cell carcinoma." (PMID 35565469, 2022). "miR-1233 directly targets cholesteryl transferase 2 (ACAT2) and is a target of circ-RPL23A, which inhibits clear cell renal cell carcinoma (ccRCC) progression by competitively binding miR-1233 and thus upregulating ACAT2 expression." (PMID 36452489, 2022). "Studies have shown that ACAT2 may suppress the progression of clear cell renal cell carcinoma (ccRCC) by promoting apoptosis of tumour cells and inhibiting epithelial-mesenchymal transition (EMT)." (PMID 38670954, 2024). "A study about clear cell renal cell carcinoma suggested that ACAT2 expression was not an independent prognostic factor of survival." (PMID 38178203, 2024).
colorectal cancer (4 papers, 2020 to 2024). A primary or metastatic malignant neoplasm that affects the colon or rectum. "Malignant progression of colorectal cancer has been linked to the pro-proliferative activity of ACAT2." (PMID 33488671, 2020). "ACAT2 could promote cell proliferation and associated with malignant progression in colorectal cancer." (PMID 35615380, 2022).
glioma (4 papers, 2017 to 2025). A benign or malignant brain and spinal cord tumor that arises from glial cells (astrocytes, oligodendrocytes, ependymal cells). "The identification of acetylation-associated proteins involved in proteosome pathway hints that ACAT2 induces elevated lysine acetylation in the metabolic process of glioma with epilepsy." (PMID 34664012, 2021). "In the study, increased ACAT2 expression and 39 upregulated lysine acetylation sites of 35 proteins were detected in glioma with seizures." (PMID 34664012, 2021). "Third, the upregulation of ACAT2 was observed in glioma with seizure based on proteomics and Western blot, while the exact mechanisms that regulated the amount of ACAT2 remain unclear." (PMID 34664012, 2021). "Upregulated ACAT2 may contribute to elevated acetylation in glioma with seizures, while downregulated ACAA2 may contribute to reduced acetylation." (PMID 34664012, 2021). "Furthermore, upregulated ACAT2 in gliomas with seizures were validated by Western blot (p = 0.003)." (PMID 34664012, 2021). "In the BrM/Glioma group, 8 DEPs (PRL, SNCA, MACF1, ACAT2, VWF, GSN, FCGBP, and F10) were selected for ROC curve analysis based on a logistic regression model." (PMID 39716938, 2025). "However, ACAT2 expression and function in glioma remain unclear." (PMID 34664012, 2021). "ACAT2 and ACAA2 were the differentially regulated enzymes in glioma with seizure." (PMID 34664012, 2021). "Genes in the mevalonate pathway (ACAT2, HMGCS1, and HMGCR) and downstream in the cholesterol biosynthetic pathway (FDPS, FDFT1, and SQLE), were all downregulated in dense NHAs but not dense glioma TS lines." (PMID 28118603, 2017).
Insulin resistance (4 papers, 2010 to 2025). Increased resistance towards insulin, that is, diminished effectiveness of insulin in reducing blood glucose levels. "On the other hand, ACAT2–/– mice were shown to be more susceptible to insulin resistance caused by a high-fat diet." (PMID 34063343, 2021). "Past research has shown that ablation of Acat2 can lead to increased plasma triglycerides (TGs) and cause mice on a high fat diet to become susceptible to insulin resistance, while Acat2 overexpression promotes cholesterol metabolism and reduces blood glucose levels." (PMID 40667248, 2025).
pancreatic cancer (4 papers, 2016 to 2024). "So far, it has been shown that elevated ACAT2 gene expression is associated with radiotherapy resistance in pancreatic cancer cells." (PMID 37958351, 2023). "Souchek’s study proved that high-expressed ACAT2 was related to pancreatic cancer radiation resistance, which could be used as a novel target for radiotherapy sensitization." (PMID 38178203, 2024). "The role of ACAT2 in pancreatic cancer and cancer development has not been fully elucidated." (PMID 37958351, 2023).
gastric cancer (3 papers, 2024 to 2025). A primary or metastatic malignant neoplasm involving the stomach. "ACAT2 was shown to both promote and inhibit cancer progression, depending on the condition and specific setting; for example, its upregulation in gastric cancer increases the proliferation rate of the cancerous cells and the likelihood of metastasis." (PMID 41010012, 2025).
liver fibrosis (3 papers, 2021 to 2025). "Furthermore, liver fibrosis was suppressed in the samples of F4MKO mice assessed by Sirius Red staining, along with the downregulation of key genes of fibrosis (Acat2, Col1a1, Col1a2, Timp2, and Tgfβ)." (PMID 37770480, 2023). "Importantly, increased cholesterol accumulation in HSCs accelerates liver fibrosis, and thus enhanced efflux through ABCA1 and ABCG1 induction while reducing ACAT2 may be additional mechanisms by which Aramchol reduces HSC fibrogenesis." (PMID 34151243, 2021).
lung carcinoma (3 papers, 2019 to 2020). "Through our analysis, we also found other eight proteins (ACAT2, PSIP1, TCERG1, DPYSL5, TUBA1A, AKR1B1, ANP32E, and TXNDC17) that have been associated with other cancers, but not in lung cancer." (PMID 32351780, 2020).